ITGB2 (integrin subunit beta 2)
Diseases named in the same sentence as ITGB2 in open-access papers (continued):
Sharing a sentence is not in itself a finding about the gene and the disease.
periodontitis (11 papers, 2015 to 2023). An acute or chronic inflammatory process that affects the tissues that surround and support the teeth. "The IPA analysis also showed the validated HLADRB4 and ITGB2 genes both downregulated in Periodontitis patients (group P), interacting via TNF on the same network of cellular compromise, inflammatory response, and infectious diseases." (PMID 32424199, 2020). "In the periodontitis group, macrophages were observed to exhibit elevated expressions of TLR4, IFNAR1 (the receptor of IFNβ), ISG15, ITGB2 (the receptor of ISG15), IL10." (PMID 37876725, 2023). "In subjects with DL plus periodontitis versus HS, three DEG were confirmed (DAB2, CD47, and HLADRB4), and in the comparison between subjects with periodontitis alone versus HS: the IGHG3 gen (IGHDL-P) was upregulated, and the ITGB2 and HLADRB4 genes were downregulated." (PMID 36233348, 2022).
lupus (10 papers, 2010 to 2026). "When we examined the effect of genetic control on sex-DEGs, we found genetic variants affecting the female-biased expression of FCGR3A in natural killer (NK) cells (rs2099684) and ITGB2 in monocytes (rs760462), both of which are associated with systemic lupus erythematosus." (PMID 42102734, 2026). "Specifically, ligand–receptor pairs such as Thy1-(Itgam+Itgb2), Mif-(Cd74+Cxcr4), Tgfb1-(Tgfbr1+Tgfbr2), and Pecam1-Pecam1 showed higher mean expression levels in lupus mice than in DHA-treated mice." (PMID 40728997, 2025). "CNVs have been widely reported in ITGB2 contributing to various subtypes of diseases, including DS, systemic lupus erythematosus, and lupus nephritis." (PMID 29649131, 2018). "Splenic B cells from NZB/NZW F1 lupus mice showed ITGB2 activation compared to normal C57Bl/6 mice." (PMID 37614232, 2023).
myeloma (10 papers, 2015 to 2024). "ITGAM, ITGB2 genes play a pivotal role in cell adhesion in multiple myeloma and are reported as potential diagnostic markers." (PMID 33946372, 2021). "Melphalan’s protein associations were highly distinct from those of bortezomib, with increased efficacy in myeloma cells with high expression levels of integrin B2 (ITGB2) and E3 ubiquitin-protein ligase TRIP12, among others." (PMID 37081258, 2023). "From a bioinformatics analysis, ITGAM and ITGB2 were also up-regulated in myeloma and involved in cytokine-cytokine receptor interaction, innate immune response and inflammatory response that were similar to our results." (PMID 35501867, 2022). "Another study revealed that ITGB2 expression was closely related to CLL and myeloma in hematological malignancies." (PMID 38345576, 2024).
myocardial infarction (10 papers, 2013 to 2025). Gross necrosis of the myocardium, as a result of interruption of the blood supply to the area, as in coronary thrombosis. "As a risk factor, ITGB2 has been implicated in accelerating myocardial infarction and arterial thrombotic cerebral infarction via cell adhesion molecular pathways." (PMID 39055656, 2024). "As a risk factor, Itgb2 had been shown to accelerate the development of myocardial infarction, atherothrombotic cerebral infarction, and diabetic nephropathy through the cell adhesion molecule pathway." (PMID 35586138, 2022). "Itgb2 is reported to be a risk factor of myocardial infarction and atherothrombotic cerebral infarction through inflammatory processes as a cell adhesion molecule." (PMID 31827539, 2019). "Itgb2 is also involved in the reducing the risk of myocardial infarction due to adverse reactions to statins." (PMID 31827539, 2019). "In a study on myocardial infarction, overexpression of ITGB2 increased the migration and improved the engraftment of adipose-derived stem cells and augmented angiogenesis." (PMID 38216708, 2024). "Itgb2 expression showed an early peak, 3 days after myocardial infarction, whereas Itgb5 mRNA levels progressively increased after 3 and 7 days." (PMID 37985764, 2023). "In the co-expression network, we found 16 genes directly involved in myocardial infarction, including Alox5ap, Itgb2 and B4galt1." (PMID 31827539, 2019).
ovarian carcinoma (10 papers, 2007 to 2026). A malignant neoplasm originating from the surface ovarian epithelium. "Many studies have demonstrated that ITGB2 is overexpressed in ovarian cancer relative to normal ovarian tissue; it is linked to metastasis and poor prognosis in ovarian cancer and can be used as a prognostic immunomarker." (PMID 38534733, 2024). "Therefore, we concluded that high expression of ITGB2-related signal pathway in ovarian cancer patients is associated with their poor prognosis." (PMID 38345576, 2024). "Thus, we concluded that ITGB2-associated signaling route (PI3K-AKT-mTOR) may contribute to the progression of cancerous traits in ovarian cancer via mediating mitochondrial glycolytic transformation." (PMID 38345576, 2024). "The results showed that ITGB2-related signal pathway expression was significantly upregulated in high-grade ovarian cancer samples (FIGO III/IV) compared with low-grade ones." (PMID 38345576, 2024). "The results showed that the number of ovarian cancer cells that crossed the basement membrane increased significantly in the ITGB2 overexpressing group, while it decreased after PI3K/AKT inhibition." (PMID 38345576, 2024). "To further demonstrate the regulatory mechanism of ITGB2 on mitochondrial glycolysis in ovarian cancer cells, we constructed ovarian cancer cell models with different signaling pathway expression levels." (PMID 38345576, 2024). "Immunohistochemical staining revealed that the protein levels of the ITGB2 signaling pathway (PI3K-AKT-mTOR) were significantly higher in ovarian cancer tissues than in normal ovarian tissues." (PMID 38345576, 2024). "In ITGB2- silenced ovarian cancer cells (A2780), the protein levels of PI3K (pi-PI3K), AKT (pi-AKT) and mTOR (pi-mTOR) decreased significantly, and the overexpression of PI3K and AKT reversed this change." (PMID 38345576, 2024). "Our research revealed a distinct increase in the expression of ITGB2 and associated signaling pathway elements (PI3K-AKT-mTOR) in cases of ovarian cancer." (PMID 38345576, 2024). "To clarify the effect of ITGB2 on the invasion of ovarian cancer cells and its possible mechanism, we used a Transwell test to evaluate changes in their invasive ability." (PMID 38345576, 2024). "Experiments on colony formation revealed a noticeable rise in the count of newly formed ovarian cancer cells in the ITGB2 overexpressing group, contrasting with a corresponding decline following the inhibition of PI3K and AKT." (PMID 38345576, 2024). "Across the databases, we also found that ITGB2 has a positive relevance to immune infiltration in a various of cancer types, including ovarian cancer." (PMID 36980477, 2023). "Results show that the relative expression of ITGB2 mRNA in the patient-derived ovarian cancer cell (PDC3) was 1.625, which was significantly upregulated (p = 0.0304 < 0.05) compared with the expression in the IOSE80 cell (mRNA = 1)." (PMID 36980477, 2023). "Our results highlight the potential ability of ITGB2 to be a regulator of immune infiltration and a marker of the response to immunotherapy for ovarian cancer patients." (PMID 36980477, 2023). "Similarly, in ovarian cancer, ITGB2 is upregulated when compared to normal tissue and a high ITGB2 expression correlate positively with the infiltration of immune cells, particularly of M2 macrophages." (PMID 40432828, 2025). "In this research we demonstrated that ITGB2 could promote glycolytic transformation through activating PI3K-AKT-mTOR axis in ovarian cancer cells." (PMID 38345576, 2024). "Based on these results, we concluded that ITGB2 could promote the tumor growth of ovarian cancer cells through the PI3K- AKT-mTOR pathway in vivo." (PMID 38345576, 2024). "Our results suggested that ITGB2 might promote cell proliferation via the PI3K-AKT-mTOR signaling pathway in ovarian cancer cells." (PMID 38345576, 2024).
ovarian carcinoma (continued). "Moreover, in the ITGB2 knockdown group, the number of newly generated ovarian cancer cells obviously decreased, and this number increased after PI3K/AKT overexpression." (PMID 38345576, 2024). "The mitochondrial energy metabolism detection showed that the levels of lactic acid, proton leakage and ATP in the mitochondria of ITGB2-overexpressing ovarian cancer cells increased significantly, while the levels of these indicators decreased after the silencing of PI3K and AKT." (PMID 38345576, 2024). "Findings indicated that the protein concentrations of PI3K (pi-PI3K), AKT (pi- AKT) and mTOR (pi-mTOR) were significantly increased in ITGB2-overexpressing ovarian cancer cells (SKOV3), and these increases could be reversed after PI3K and AKT inhibition." (PMID 38345576, 2024). "Our findings revealed a simultaneous presence of mitophagy and lysosome markers, indicating a clear rise in the joint presence of LC3 and LAMP2 in ovarian cancer with reduced ITGB2 levels, while PI3K/AKT up-regulation could save this pathological change." (PMID 38345576, 2024). "Therefore, we concluded that the ITGB2-related axis plays an important role in regulating malignant phenotypes in ovarian cancer cells." (PMID 38345576, 2024). "Here, we developed a xenograft mouse model to determine whether ITGB2 affects the oncogenic progression of ovarian cancer cells (SKOV3) in vivo." (PMID 38345576, 2024). "Concurrently, TEM analysis of mitochondrial structure revealed that in ovarian cancer cells with ITGB2 knockdown, there was a noticeable decrease in mitochondrial size, rupture of the mitochondrial membrane, and vanishing of mitochondrial cristae, in contrast to normal cells." (PMID 38345576, 2024). "Moreover, the levels of lactic acid, proton leakage and ATP in the mitochondria of ITGB2 knockdown ovarian cancer cells clearly decreased, while the levels of these indicators correspondingly increased after the overexpression of PI3K and AKT." (PMID 38345576, 2024). "Several researchers believe that ITGB2 might be involved in the emergence and progression of ovarian cancer." (PMID 38345576, 2024). "At the same time, in ITGB2 knockdown ovarian cancer cells the expression of these enzymes obviously decreased, while the overexpression of PI3K-AKT could rescue this process." (PMID 38345576, 2024). "Based on these results we concluded that ITGB2 could promote mitochondrial glycolysis and energy conversion in ovarian cancer cells through PI3K-AKT-mTOR axis." (PMID 38345576, 2024). "Many academics hold the view that ITGB2 could encourage the advancement of ovarian cancer via PI3K-AKT-mTOR signalling pathway mediated mitochondrial glycolysis." (PMID 38345576, 2024). "ITGB2 (CD18) is one of the key subunits of β2 integrin, and bioinformatic analysis revealed that ITGB2 expression was upregulated in high-risk groups and significantly correlated with the overall survival time in ovarian cancer patients." (PMID 38345576, 2024). "The results revealed that the expression of critical glycolytic enzymes (such as Glu, T4MCT4 and LdhB) in ITGB2 overexpressing ovarian cancer cells was obviously upregulated compared with that in the NC group, while the knockdown of PI3K and AKT reversed this change." (PMID 38345576, 2024). "Existing ovarian cancer studies suggest that ITGB2 targeted therapy should be explored." (PMID 38534733, 2024). "Furthermore, we identified the specific expression of ITGB2 in both ovarian cancer patient-derived cells and tumor tissues." (PMID 36980477, 2023). "In summary, this study revealed that ITGB2 might function as a prognostic biomarker in ovarian cancer and might lay the groundwork for the landscape of immuno-therapy strategies in advanced serous ovarian cancer." (PMID 36980477, 2023). "Additionally, we confirmed that ITGB2 was over-expressed in ovarian cancer tissues and was mainly located in cytoplasm, detected by Western blotting and the immunohistochemical method." (PMID 36980477, 2023).
ovarian carcinoma (continued). "Moreover, the levels of oxygen consumption, basal respiration, maximal respiration and spare respiratory capacity in the mitochondria of ITGB2 overexpressing ovarian cancer cells clearly decreased, while the levels of these indicators correspondingly increased after the inhibition of PI3K and AKT." (PMID 38345576, 2024). "Thus, we concluded that ITGB2 signal pathway (PI3K-AKT-mTOR) could enhance mitochondrial glycolysis in ovarian cancer cells through upregulating rate-limiting enzymes." (PMID 38345576, 2024). "The results of a bioinformatics analysis showed that ITGB2 expression levels were significantly correlated with overall survival time in ovarian cancer cases; therefore, several scholars suggest that ITGB2 might be involved in the progression of ovarian cancer." (PMID 38345576, 2024). "Therefore, we concluded that ITGB2 could promote the invasion ability of ovarian cancer cells via the PI3K/AKT/mTOR pathway." (PMID 38345576, 2024). "In summary, ITGB2 may serve as a prognostic immunomarker for ovarian cancer patients." (PMID 36980477, 2023). "Thus, this study identified, for the first time, that ITGB2 may act as a novel prognostic immunomarker for ovarian cancer patients." (PMID 36980477, 2023). "In the FISH experiment, we noticed that ITGB2-AKT (green) and PI3K (red) were situated within the cytoplasm of ovarian cancer cells." (PMID 38345576, 2024). "Our research showed that ITGB2 expression was upregulated and that its downstream signaling pathway (PI3K-AKT-mTOR) was activated in ovarian cancer samples." (PMID 38345576, 2024). "The results revealed that ITGB2 and its downstream pathway factors (PI3K-AKT-mTOR) were obviously upregulated in ovarian cancer cells compared with normal ones." (PMID 38345576, 2024). "To explore the effect of ITGB2-mediated PI3K-AKT-mTOR pathway regulation on mitochondrial glycolysis in ovarian cancer cells, we constructed ovarian cancer cell models with different ITGB2, PI3K and AKT expression levels." (PMID 38345576, 2024). "Here, we used immunohistochemical staining to study the expression of ITGB2 and its related signal pathway (PI3K-AKT-mTOR) in different stages (FIGO I-IV) of ovarian cancer samples." (PMID 38345576, 2024). "Siglec-9, the receptor of MUC16, had strong correlations with markers of neutrophil ITGAM, ITGB2, FCGR1A, FCGR2A, FCGR3A, analyzed with TCGA-OV database and ovarian cancer tissue RNA sequencing data." (PMID 37644468, 2023). "TYROBP, ITGB2, C1QB, C1QA and CD53 in module B have the top connectivity among all DEGs and are considered to have important relationship to immune response in ovarian cancer." (PMID 33987033, 2021). "By PPI network and MCODE module, TYROBP, ITGB2, C1QB, C1QA, CD53 and CD163 have top connectivity among all DEGs and are considered to have important relationship to immune response in ovarian cancer." (PMID 33987033, 2021). "Consequently, it was deduced that ITGB2 has the potential to suppress mitophagy and preserve the steadiness of MMP in ovarian cancer cells via PI3K/AKT/mTOR signaling route." (PMID 38345576, 2024). "Therefore, we concluded that the expression of ITGB2 and its related signaling pathway (PI3K-AKT-mTOR) were upregulated in ovarian cancer samples." (PMID 38345576, 2024). "ITGB2 might control mTOR expression via the PI3K-AKT pathway, thus promote mitochondrial glycolysis transformation and cell energy supply in ovarian cancer." (PMID 38345576, 2024). "Subsequently, the survival and immune infiltration analysis demonstrated that the upregulation of five candidate genes, ITGB2, VEGFA, CLDN4, OCLN, and SPP1, were correlated with an unfavorable clinical outcome and increased immune cell infiltration in ovarian cancer." (PMID 36980477, 2023).
ovarian carcinoma (continued). "Our results showed that ITGB2 related signal pathway (PI3K-AKT-mTOR) could promote cellular energy supply through mediating glycolytic transformation, thus inhibited mitophagy and maintained mitochondrial stability, finally encouraged the growth and infiltration of ovarian cancer cells." (PMID 38345576, 2024). "In this research we successfully proved that ITGB2 expression could promote glycolytic transformation in mitochondria through activating PI3K-AKT-mTOR signal pathway, thereby preserving mitochondrial stability and fostering malignant characteristics in ovarian cancer cells." (PMID 38345576, 2024).
Arthritis (9 papers, 2014 to 2023). Inflammation of a joint. "The fact that STK10, ITGB2, SLC9A3R1, and SLC9A3R2 are related to inflammation and arthritis strengthens our findings that these proteins reflect the arthritic process." (PMID 38274452, 2023).
oral squamous cell carcinoma (9 papers, 2020 to 2025). "In recent years, it has been found that ITGB2 mediates a metabolic switch in cancer-associated fibroblasts, promoting oral squamous cell carcinoma proliferation." (PMID 38216708, 2024). "ITGB2 regulates metabolic switch in cancer-associated fibroblasts through mitochondrial oxidative phosphorylation of NADH to promote oral squamous cell carcinoma proliferation." (PMID 35185791, 2022). "A prospective study revealed that high ITGB2 expression in cancer-associated fibroblasts promoted tumor proliferation in oral squamous cell carcinoma through NADH oxidation in the mitochondrial oxidative phosphorylation system." (PMID 34136377, 2021). "Meanwhile, ITGB2 is involved in the progression of oral squamous cell carcinoma via the PI3K-AKT-mTOR pathway." (PMID 37954130, 2023). "Interestingly, a study has shown that ITGB2 could activate the PI3K/AKT/mTOR axis to promote proliferation in oral squamous cell carcinoma by nicotinamide adenine diphosphate hydride oxidation." (PMID 34108992, 2021). "ITGB2 was correlated with higher TNM stages and promotes proliferation in oral squamous cell carcinoma." (PMID 34108992, 2021).
rheumatoid arthritis (9 papers, 2014 to 2025). A chronic, systemic autoimmune disorder characterized by inflammation in the synovial membranes and articular surfaces. "Similarly, in KEGG of “ Rheumatoid Arthritis”, we found that although Itgb2 and Cxcl12 do not act directly, they can cooperate in the activation of immune cells and VEGF signaling pathway to promote the inflammatory cells migration and angiogenesis." (PMID 37063847, 2023).
colorectal cancer (8 papers, 2017 to 2025). A primary or metastatic malignant neoplasm that affects the colon or rectum. "For instance, in vitro, ITGB2‐deficient colorectal cancer cells show reduced proliferation, adhesion, and migration, and they fail to activate liver sinusoidal endothelial cells, which are essential for creating a TME conducive to liver metastasis." (PMID 40071217, 2025). "Additionally, the expression of ITGB2 was upregulated in IBD‐associated colorectal cancer (CRC)." (PMID 39088353, 2024).
fungal infections (8 papers, 2010 to 2025). "This condition arises from mutations in ITGB2, the gene encoding the β subunit (CD18) of the β2 integrins, leading to recurrent, life-threatening bacterial and fungal infections." (PMID 39081307, 2024). "Leukocyte adhesion deficiency type 1 (LAD1) is caused by mutations on ITGB2 (CD18) gene in humans, which are affected by recurrent bacterial and fungal infections." (PMID 36263057, 2022).
Immunodeficiency (8 papers, 2008 to 2025). Failure of the immune system to protect the body adequately from infection, due to the absence or insufficiency of some component process or substance. "Moreover, SCLC patients with high ITGB2 expression had lower tumor immune dysfunction and exclusion scores, and the proportion of urothelial cancer patients with complete response/partial response was observably decreased in ITGB2high group." (PMID 39960961, 2025). "While CD40, CD44, CKLF and ITGB2 (CD18) mRNAs were significantly upregulated in ICF vs. control LCLs, their positive functions in lymphogenesis make them unlikely candidates for active players in the immunodeficiency of ICF patients." (PMID 18432406, 2008).